FBXL4 (F-box and leucine rich repeat protein 4)
Diseases named in the same sentence as FBXL4 in open-access papers (continued):
Sharing a sentence is not in itself a finding about the gene and the disease.
cancer (2 papers, 2017 to 2024). A tumor composed of atypical neoplastic, often pleomorphic cells that invade other tissues. "The strong correlation of FBXL4 loss and Gleason score is consistent with our in vitro observation that FBXL4 is associated with cancer cell migration and invasion." (PMID 28698647, 2017). "Loss of FBXL4 copy number may be the main mechanism that leads to low expression of this gene and resulting haplo-insufficiency may contribute to cancer progression." (PMID 28698647, 2017). "The biological role of FBXL4 in suppressing cancer progression to advanced disease was also confirmed by the strong associations between FBXL4 loss and high Gleason score, advanced clinical stage, high PSA and large disease volume in a cohort of conservatively managed localised prostate cancer." (PMID 28698647, 2017). "Identification of the proteins which are associated with cell invasion and aggressive disease and whose degradation is controlled by FBXL4, such as ERLEC1, has the potential to develop targeted therapies for a large number of lethal human cancers with loss of FBXL4." (PMID 28698647, 2017). "Loss of FBXL4 may contribute to cancer cell distribution patterns associated with higher Gleason scores and therefore are both associated with bone metastasis and poor prognosis." (PMID 28698647, 2017). "FBXL4 potentially controls cancer metastasis through regulation of ERLEC1 levels." (PMID 28698647, 2017). "Using FBXL4 copy number change as a prognostic marker and targeting the downstream pathways of FBXL4 for cancer treatment may have a much broader application than bone metastatic prostate cancer." (PMID 28698647, 2017). "Apart from the link between rare autosomal recessive FBXL4 loss-of-function and splice mutations and early-onset mitochondrial encephalomyopathy, there are no reports on FBXL4 function and potential involvement in cancer." (PMID 28698647, 2017). "Thus FBXL4 may prevent cancer metastasis through regulation of ERLEC1 protein levels." (PMID 28698647, 2017).
autosomal recessive disease (1 paper, 2025). Autosomal recessive form of disease. "MTDPS13 is a rare autosomal recessive disease induced by biallelic mutations in the F-box and leucine-rich repeat (LRR) protein 4 gene (FBXL4), characterized by increased mitochondrial autophagy and mitochondrial DNA (mtDNA) depletion in FBXL4 knockout mice and patient fibroblasts." (PMID 40352787, 2025).
infection (1 paper, 2025). The state of being infected such as from the introduction of a foreign agent such as serum, vaccine, antigenic substance or organism. "Conclusively, FBXL4-MTDPS may be involved in intrinsic defects in infection defense, particularly in the lungs." (PMID 41142849, 2025).
FBXL4 also shares sentences with these, for which no sentence is quoted: developmental delay (3 papers); Failure to thrive (2); microcephaly (2); Arrhythmia (1); benign prostatic hyperplasia (1); biotinidase deficiency (1); Birk-Landau-Perez syndrome (1); bone metastasis (1); breast carcinoma (1); cataract (1); Cerebellar atrophy (1); cone-rod dystrophy (1); congenital rubella syndrome (1); Dihydrolipoamide dehydrogenase deficiency (1); dilated cardiomyopathy (1); Down syndrome (1); encephalomyopathy (1); epilepsy (1); Epileptic encephalopathy (1); Huntington disease (1); hypertrophic cardiomyopathy (1); immune dysfunction (1); Leigh syndrome (1); limb girdle muscular dystrophy type 2S (1); liver dysfunction (1); lymph node metastasis (1); lymphopenia (1); migraine headache (1); Mitochondrial myopathy (1); mucopolysaccharidosis type 2 (1).
A further 12 diseases each share a sentence with FBXL4 in 1 paper.